VAMP5 (vesicle associated membrane protein 5)
Description:
May participate in trafficking events that are associated with myogenesis, such as myoblast fusion and/or GLUT4 trafficking.
Tractability: Antibody: UniProt places it where antibodies can reach, with high confidence; its Gene Ontology location is reachable by antibodies, with high confidence; UniProt predicts a signal peptide or a membrane-spanning region; the Human Protein Atlas places it where antibodies can reach. PROTAC: ubiquitination databases record sites on it; its protein half-life has been measured.
Gene: Protein-coding gene on chromosome 2 (85,584,431 to 85,593,406, forward strand). Ensembl gene ENSG00000168899.
Subcellular location: Cell membrane; Endomembrane system; Golgi apparatus, trans-Golgi network membrane
Subcellular location (Human Protein Atlas): Nucleoplasm; Plasma membrane
Gene Ontology:
Molecular function: protein binding
Biological process: Golgi to plasma membrane protein transport; muscle organ development; vesicle-mediated transport
Cellular component: cell surface; extracellular exosome; cytoplasmic vesicle membrane; late endosome; perinuclear region of cytoplasm; plasma membrane; endomembrane system; Golgi apparatus; intercalated disc; membrane; trans-Golgi network
Genetic constraint (gnomAD): Loss-of-function variants: 10 observed, 9.9 expected, observed/expected ratio (o/e) 1.01, 90% interval 0.62 to 1.67. That is too few expected variants to judge how well the gene tolerates losing a copy. Missense variants: 135 observed, 160.44 expected, observed/expected ratio (o/e) 0.84, 90% interval 0.73 to 0.97. Synonymous variants: 62 observed, 64.11 expected, observed/expected ratio (o/e) 0.97, 90% interval 0.79 to 1.2.
Homologues: Orthologues: chimpanzee VAMP5 (98% identical), macaque VAMP5 (84% identical), rabbit VAMP5 (74% identical), pig VAMP5 (72% identical), guinea pig VAMP5 (65% identical), mouse Vamp5 (64% identical), dog VAMP5 (63% identical), rat Vamp5 (62% identical), zebrafish vamp5 (31% identical), Drosophila melanogaster Syb (28% identical), Caenorhabditis elegans snb-2 (27% identical), Caenorhabditis elegans snb-6 (18% identical), and 2 more. Paralogues in human: VAMP2 (30% identical), VAMP3 (29% identical), VAMP1 (28% identical), VAMP8 (22% identical), VAMP7 (21% identical), VAMP4 (20% identical), YKT6 (16% identical), SEC22B (14% identical), SEC22A (12% identical), SEC22C (9% identical).
Diseases named in the same sentence as VAMP5 in open-access papers:
VAMP5 is named in the same sentence as 16 diseases in open-access papers, as found by Europe PMC text mining. Sharing a sentence is not in itself a finding about the gene and the disease. The quoted sentences say what the papers report.
glioma (4 papers, 2020 to 2024). A benign or malignant brain and spinal cord tumor that arises from glial cells (astrocytes, oligodendrocytes, ependymal cells). "Vesicle-associated membrane protein 2 (VAMP2) and vesicle-associated membrane protein 5 (VAMP5) were identified as two SRGs affecting the prognoses of glioma patients." (PMID 38115820, 2023). "We constructed a risk model based on the expression of VAMP2 and VAMP5 in gliomas." (PMID 38115820, 2023). "VAMP5 protein level showed an insignificant increase in different grades of gliomas, but it was significantly higher in glioma tissues than in normal tissues." (PMID 38115820, 2023). "QRT-PCR assay showed that VAMP2 mRNA was gradually decreased with the increase of WHO grades, and that it reached the lowest level in WHO 4 gliomas compared to normal tissues, while VAMP5 mRNA showed the opposite changes." (PMID 38115820, 2023). "We then performed a multivariate Cox regression analysis, and the results showed that two SRGs (VAMP2 and VAMP5) had significant prognostic value in gliomas." (PMID 38115820, 2023). "Here we found that VAMP2 and VAMP5 were two key genes in the SNARE family that affected the prognosis of glioma patients." (PMID 38115820, 2023). "Our study confirmed that the expression levels of VAMP2 and VAMP5 genes were significantly associated with survival time, WHO classification, IDH, and co-deletion status of 1p19q in glioma patients." (PMID 38115820, 2023). "More importantly, we verified the changes of VAMP2 and VAMP5 at both mRNA and protein levels in glioma specimens and cell lines." (PMID 38115820, 2023). "We next validated the changes of VAMP2 and VAMP5 at both mRNA and protein levels in glioma specimens and cell lines stored in our institute." (PMID 38115820, 2023). "More importantly, we verified the changes of VAMP2 and VAMP5 at both mRNA and protein levels in different grades of gliomas collected from our hospital." (PMID 38115820, 2023). "In addition, we found low expression of VAMP2 and high expression of VAMP5 in different glioma cell lines (U87, A172, LN229, U251, U373) compared to a human astrocyte line (HA1800)." (PMID 38115820, 2023). "Thus, co-culture systems of neurons or immune cells with glioma cells are required to reveal the roles of VAMP2 and VAMP5 in the TME of gliomas." (PMID 38115820, 2023). "VAMP5 was observed to be correlated in tumor microenvironment of brain lower grade glioma." (PMID 33169786, 2020). "According to the Gene Expression Profile Interaction Analysis (GEPIA) online analysis, VAMP5 expression was significantly higher, while VAMP2 expression was significantly lower in gliomas than in normal samples." (PMID 38115820, 2023). "Therefore, VAMP2 and VAMP5 may play an important role in the progression of gliomas." (PMID 38115820, 2023). "In this study, we constructed a novel risk model for predicting the prognosis and immune microenvironment of glioma patients based on the expression of SNARE proteins VAMP2 and VAMP5." (PMID 38115820, 2023). "Secondly, we identified VAMP2 and VAMP5 as two key SNARE proteins affecting the prognoses of gliomas, but the lack of experimental evidences in glioma cells or models limits the interpretation of this finding." (PMID 38115820, 2023).
bladder cancer (1 paper, 2024). "In conclusion, we have developed and validated a novel tumor-specific T cell signature (including VAMP5, TIGIT, LCK, CD27, and CACYBP) as a prognostic biomarker for bladder cancer patients treated with immunotherapy using single cell multi-omics data." (PMID 39033098, 2024). "We developed a five-gene signature (including VAMP5, TIGIT, LCK, CD27 and CACYBP) based on tumor-specific T cell-related genes to predict the immunotherapy response in bladder cancer patients." (PMID 39033098, 2024). "Furthermore, Kaplan-Meier survival analysis revealed that the higher expression of VAMP5, TIGIT, LCK, CHORDC1, CD27, and CACYBP was correlated with better outcomes in bladder cancer patients treated with immunotherapy." (PMID 39033098, 2024). "Therefore, our study aimed to investigate the role of tumor-specific T cells in bladder cancer immunotherapy by constructing TstcSig, consisting of five tumor-specific T cell-related genes: CD27, CACYBP, TIGIT, LCK, and VAMP5." (PMID 39033098, 2024).
colorectal cancer (1 paper, 2018). A primary or metastatic malignant neoplasm that affects the colon or rectum. "This study aims to investigate the association of vesicle-associated membrane protein 5 (VAMP5) and mutated in colorectal cancer (MCC) genetic polymorphisms and their correlated risks with HSCR." (PMID 29695640, 2018).
gastric cancer (1 paper, 2016). A primary or metastatic malignant neoplasm involving the stomach. "Therefore, we suggested that other regulators may exist in regulating the expressions of POLG and VAMP5 in gastric cancer." (PMID 26897165, 2016).
sarcoma (1 paper, 2020). A usually aggressive malignant neoplasm of the soft tissue or bone. "After performing validation in both TCGA dataset and GEO dataset GSE17679, we extracted a group of immune-related genes, including NR1H3, VAMP5, GIMAP2, GBP2, HLA-E and CRIP1 that were most significant to predict good outcomes in sarcoma patients." (PMID 33316779, 2020).
vitiligo (1 paper, 2025). Generalized well circumscribed patches of leukoderma that are generally distributed over symmetric body locations and is due to autoimmune destruction of melanocytes. "This analysis identified four genes—STAT1, VAMP5, LAP3, and TYMP—that exhibited both strong module membership and significant upregulation in vitiligo." (PMID 41498037, 2025).
tumor (4 papers, 2016 to 2024). "Bioinformatic analysis of some immune-related genes has shown that VAMP5 is associated with immune infiltration in some tumor types." (PMID 38115820, 2023). "VAMP5, as a crucial molecule mediating vesicle-mediated transport and Golgi to plasma membrane protein transport processes, has a role in promoting tumor progression, but is less studied." (PMID 38115820, 2023). "qPCR quantification of the relative expression of the five candidate genes LOXL1, SCRN1, VAMP5, SERPINB1, and TMSB4X in cryopreserved tumor tissues from validation set 1 was correlated to the CSIs measured in the corresponding fresh tissue samples of the same tumor lesions." (PMID 26799424, 2016).
infection (1 paper, 2024). The state of being infected such as from the introduction of a foreign agent such as serum, vaccine, antigenic substance or organism. "VAMP5 is significantly upregulated in TB patients upon infection, which indicates the key role of the VAMP5 protein in the TB immune process." (PMID 38674369, 2024).
VAMP5 also shares sentences with these, for which no sentence is quoted: cancer (2 papers); brucellosis (1); cognitive decline (1); diabetes (1); Hematological Disease (1); hepatocellular carcinoma (1); Hirschsprung disease (1); sarcopenia (1).